PCA3 (prostate cancer associated 3)
Diseases named in the same sentence as PCA3 in open-access papers (continued):
Sharing a sentence is not in itself a finding about the gene and the disease.
prostate carcinoma (continued). "Some of these genes were already extensively studied in prostate cancer, mostly those upregulated in tumor tissue: SPINK1 (Top17, logFC 4.8), ETV4 (Top63, logFC 3.6), PCA3 (Top79, logFC 3.5), TDRD1 (Top86, logFC 3.4), AMACR (Top105, logFC 3.2), DLX1 (Top110, logFC 3.1), HOXC6 (Top268, logFC 2.3)." (PMID 31170942, 2019). "Differential display analysis of human prostate cancers identified Differential display 3, also known as PCA3, this lncRNA was approved by the Food and Drug Administration (FDA) for prostate cancer diagnosis and was the first case of a lncRNA being used for clinical testing by FDA approval." (PMID 29329543, 2018). "PCA3 has been shown to be a specific biomarker for prostate cancer and act as a negative oncogenic regulator of the tumor suppressor gene PRUNE2." (PMID 29732012, 2018). "PCA3, also called DD3, is a prostate-specific gene that is highly overexpressed in prostate cancer." (PMID 29386530, 2018). "However, the function of PCA3 and PCAT9 in prostate cancer progression, including migration, angiogenesis, and cancer-related stemness, has not been fully understood." (PMID 29552304, 2018). "The expression of PCA3 and PCA3-shRNA2 did not vary significant when stratified by time of prostate cancer diagnosis from initial biopsy." (PMID 28380027, 2017). "Since PCA3 is an emerging biomarker for prostate cancer, and that the expression of the TG STR in PCA3 gene is regulated by anti-androgen therapy in this study, we selected the TG-PCA3 STR for a genetic association analysis in a large cohort of prostate cancer patients and controls." (PMID 29203868, 2017). "Several lncRNAs have been used as diagnostic and prognostic markers, including the following: MALAT-1 for liver, lung, breast, and prostate cancer; HOTAIR for breast, brain, and colon cancer; OOC1 for colon cancer; and PCA3, PCAT-1, and SChLAP1 for prostate cancer." (PMID 26160837, 2015). "The consensus in most publications is that PCA3 can help distinguish between individuals with and without prostate cancer." (PMID 25526029, 2014). "Likewise, some recent studies have also reported the presence of PCA3 and TMPRSS2-ERG fusion, two known prostate cancer biomarkers, in exosomes from urine samples of prostate cancer patients." (PMID 26317031, 2014). "Individuals with prostate cancer compatible with AS had significantly lower phi and PCA3 values than those who did not match PRIAS criteria (p<0.001 and p = 0.01, respectively)." (PMID 23861782, 2013). "Although the gene signatures of all forms of urogenital cancer/diseases are largely unknown, the six known prostate cancer genes of AGR2, AMACR, CRISP3, ERG, HPN, and PCA3 are at or below background, for example, in bladder cancer." (PMID 23029164, 2012). "We hypothesized that the immunomagnetic enrichment method described herein could be used together with PCA3 and TMPRSS2:ERG assays to specifically detect CTCs in advanced prostate cancer." (PMID 20598135, 2010). "Detection of PCA3 and/or TMPRSS2:ERG mRNA in whole blood could potentially be used as a prognostic indicator of aggressive prostate cancer." (PMID 20598135, 2010). "Additionally, this study supports the report by De Luca and colleagues which suggested that PCA3 could be a main determinant for prostatitis, high-grade prostatic intraepithelial neoplasia (HG-PIN), and prostate cancer." (PMID 36246565, 2022). "Notably, despite the increasing number of publications about the putative utility of circulating non-coding (ncRNAs) as clinical biomarkers, urinary lncRNA PCA3 is the only circulating RNA approved by the FDA for molecular testing and used to complement PSA for management of early prostate cancer." (PMID 34638230, 2021). "The specificity for prostate cancer detection on biopsy could be improved by fixing the sensitivity at 95%, with individual specificities of 15% for PSGR, 17% for PCA3, and 34% for the PSGR and PCA3 duplex panel." (PMID 31013716, 2019).
prostate carcinoma (continued). "Secondly, PCA3 expression is increased exclusively in patients diagnosed with prostate cancer but not benign prostatic hyperplasia (BPH), prostatic intraepithelial neoplasia (PIN), atypical small acinar proliferation (ASAP), inflammation, or chronic prostatitis." (PMID 28272371, 2017). "The highly amplified PCA3-3STA activity was restricted to PCa cell lines (22Rv1, LAPC4, PC-3 and DU145) but remained inactive in benign prostate cell lines (PZ-HPV7 and WPMY-1) and non-prostate carcinoma cell lines such as SW780 (bladder), MGHU3 (bladder) and HepG2 (hepatic)." (PMID 26594800, 2016). "Increased PCA3 in biopsy tissue correlated with prostate cancer and the PCA3 assay may improve the diagnosis efficacy as the PCA3 score being independent of PSA level." (PMID 26628213, 2015). "The prostate cancer antigen gene 3 (PCA3) is embedded in an intron of a second gene BMCC1 (Bcl2-/adenovirus E1B nineteen kDa-interacting protein 2 (BNIP-2) and Cdc42GAP homology BCH motif-containing molecule at the carboxyl terminal region 1) which is also upregulated in prostate cancer." (PMID 24040105, 2013). "Using a histogram format for data display, all signal counts for the selected prostate cancer genes were at background for P08-022N: AGR2 = 0.08 [(8 counts, relative to B2M = 100 (10,000 counts)], AMACR = 0.46, CD90v = 0.02, CRISP3 = 0.25, ERG = 0.1, HPN = 0.04, PCA3 = 0.09 (data entries in blue)." (PMID 23029164, 2012). "Importantly, urinary PCA3 levels do not correlate with prostate volume but correlate with tumour aggressiveness as described by the Gleason score, thus reflecting the aggressiveness of prostate cancer." (PMID 37143733, 2023). "Unlike serum prostate specific antigen (PSA) levels, PCA3 is not affected by the prostate volume or non-cancerous prostate hyperplasia, making it a particularly useful biomarker, especially for identifying patients with clinically insignificant prostate cancer." (PMID 33800703, 2021). "Moreover, due to the cancer- and lineage-specific expression pattern of lncRNAs, a group of lncRNAs have proven to be prospective biomarkers, e.g., PCA3 and PCAT14 in prostate cancer, which could be used for the early detection, diagnosis, and follow-up in the clinic." (PMID 34322486, 2021). "In our study, the combination of all three mRNA expressions did not improve the prediction of clinically significant prostate cancer (AUC 0.74) compared to using PSMA and PCA3 alone (AUC 0.82 and 0.75, respectively)." (PMID 39859417, 2025). "Although a tumor-specific marker for prostate cancer is not available as yet, the advent of PSA and its derivatives, like PSA-IgM, as well as other markers, like PCA-3, has been investigated with the aim to support the early diagnosis of prostate cancer." (PMID 37746271, 2023). "PCA3, previously known as prostate cancer antigen 3 and as DD3, is a nonprotein coding RNA that is highly expressed in prostate cancer tumors." (PMID 33490732, 2021). "Pearson correlations with age are 0.40 for PCA3 and 0.15 for PSA among those without prostate cancer, and 0.24 for PCA3 and 0.28 for PSA among those with prostate cancer." (PMID 26883772, 2016). "For instance, some biomarkers such as PCA3 and TMPRSS2 are mRNAs not easily detected in body fluids, but are found in exosomes in prostate cancer." (PMID 26919248, 2016). "The combined ratio of PCA3 and PCA expression in prostate cells extracted from urine, can indicate the likelihood of prostate cancer, even if biopsies return a negative result; providing a rationale for the use of multiple biomarkers." (PMID 26473288, 2015). "Importantly for six of the eight candidates, (TRIB1, PCA3, GRHL2, ACTG2, GSN, and MXI1) we were able to confirm the differential expression of the genes that harbor these STRs using a large dataset of prostate cancers compared to adjacent non-malignant cells." (PMID 29203868, 2017).
prostate tumor (25 papers, 2008 to 2025). "The test measures the expression levels of three exosomal RNA biomarkers—ERG (ETS-related gene), PCA3 (prostate cancer antigen 3), and SPDEF (SAM pointed domain-containing ETS transcription factor)—which are associated with prostate tumor formation." (PMID 41374944, 2025). "LncRNA PCA3 is ahighly expressed lncRNA in prostate tumors, and urine PCA3 testing is the firstcancer detection method based on lncRNA that has been translated into clinicalpractice." (PMID 39308299, 2024). "Prostate cancer associated 3 (PCA3) gene, first named as DD3, is a prostate tumor-specific biomarker with high transcriptional levels detected in the blood, biopsies, and urine." (PMID 38896642, 2024). "Prostate cancer antigen 3 (PCA3), the highly prostate-specific lncRNA overexpressed in more than 95% of primary prostate tumors, was developed as a urine test for the supplementary diagnosis of prostate cancer (PCa)." (PMID 36514044, 2022). "Amongst the lncRNAs most characterized as clinically relevant is prostate cancer antigen 3 (PCA3), a unique, atypically alternatively spliced lncRNA mapped to the long arm of human chromosome 9q21–22 and overexpressed in >95% of primary prostate tumors." (PMID 33672595, 2021). "PCA3 is a prostate-specific lncRNA and is overexpressed in > 90% of primary prostate tumors compared to benign tissues, which can be detected in patient urine samples and is undetectable in other tumor types." (PMID 30466456, 2018). "A recent study has shown a potential method by which PCA3 increases prostate cell proliferation and prostate tumor growth in a xenograft model." (PMID 29203868, 2017). "To expand our initial observations regarding the expression of PCA3 in prostate cancer, we used an array-based approach to profile a large cohort of 8,532 and 1,694 prostate tumors from prospective RP and biopsy tissues, respectively." (PMID 28881605, 2017). "The sensitivity of this assay, however, is low since 40–50% of prostate tumors carry this fusion, but it can be improved in combination with PCA3." (PMID 28031932, 2016). "Previous studies indicate that prostate cancer antigen 3 (PCA3) is highly expressed in prostatic tumors." (PMID 27161545, 2016). "Next, we assessed the expression of both the canonical long form of TG2 (TGM2_v1) and the alternative truncated transcript TGM2_v2, in 57/101 patients’ biopsies after the exclusion of PCA3− biopsies from the prostate tumour group and PCA3+ biopsies from the prostate inflammation group." (PMID 37160910, 2023). "PCA3 was significantly higher in tumors with 11-repeats allele compared to tumors with the 12-repeats allele (P = 0.049), suggesting that TG-PCA3 STR may regulate PCA3 expression in prostate tumor." (PMID 29203868, 2017). "The present study was designed to assess the feasibility of an immunomagnetic enrichment method for detecting circulating prostate tumor cells using research prototype TMA assays for prostate-specific mRNAs (PSA, PCA3 and the TMPRSS2:ERG gene fusion)." (PMID 20598135, 2010). "We identified three distinct clusters within prostate tumor cells: PCA1, PCA2, and PCA3." (PMID 39743630, 2025). "PCA3 is a prostate-specific gene that is highly overexpressed in prostatic tumors in comparison to non-neoplastic prostatic tissue of the same patients, permitting its detection in cancer cells shed into urine after DRE." (PMID 38201592, 2023). "Subjects included in this study had histopathological confirmation of prostatic disease, pathology tumor grade and stage, while contamination with prostate tumor cells in the collected PP adipose tissue samples was excluded by the absence of PCA3 expression." (PMID 23009291, 2012). "The literature suggests that aggressive prostate tumors frequently demonstrate dysregulation of androgen receptor (AR) signaling, alterations in ETS transcription factors due to TMPRSS2-ERG fusion events, and overexpression of clinically monitored biomarkers such as PCA3." (PMID 41375053, 2025).
prostate tumor (continued). "Notably, a closer examination of the cellular makeup within the prostate tumor cells revealed that in four out of the five post-treatment specimens, there was an increase in the cell proportions of PCA2 and PCA3 cells, along with a decrease in the proportion of PCA1 cells." (PMID 39743630, 2025). "However, PCA3 (Prostate Cancer Antigen 3) is a long non-coding RNA (lncRNA) biomarker with 3922 nucleotides and is mainly overexpressed only in prostate tumors without apparent connection to other prostate gland abnormalities." (PMID 39589993, 2024). "The PCA3 gene is a highly specific prostate tumor biomarker that is not found in other kinds of cells and tissues, whereas its detection on peripheral blood may indicate a possible metastasis." (PMID 18823560, 2008). "The EPI measures the mRNA copy number of three genes, ERG, PCA3, and SPDEF, in the exosomes of prostate tumor cells released into the urine without DRE." (PMID 39081487, 2024).
benign prostatic hyperplasia (12 papers, 2010 to 2025). A non-cancerous nodular enlargement of the prostate gland. "Additionally, markers such as GalNac-T3 (N-acetylgalactosaminyltransferase 3), prostate-specific membrane antigen (PSMA), hepsin, and prostate cancer antigen 3 (PCA3) assist in differentiating PCa from benign prostatic hyperplasia." (PMID 40863209, 2025). "Furthermore, based on PCA3 levels in urine, this technique differentiated PCa patients from both healthy controls and benign prostatic hyperplasia (BPH) patients." (PMID 39188554, 2023). "We then evaluated the expression levels of lncRNA PCA3 and MALAT1 (metastasis-associated lung adenocarcinoma transcript 1) in a large cohort of PCa and BPH (benign prostatic hyperplasia) participants." (PMID 34439239, 2021). "The relative PCA3 expression of PCa patients determined by this assay was significantly greater than that of benign prostatic hyperplasia (BPH) patients and healthy controls." (PMID 32398974, 2020). "PCA3 mRNA levels have been detected in primary and metastatic PCa tissue specimens at up to 43 and 110 times the levels expressed in normal prostate tissue, respectively, compared with up to a 3 fold increase in benign prostatic hyperplasia (BPH)." (PMID 24281110, 2010). "PCA3 was absent in non-prostatic tissues, but present in normal prostates and benign prostate hypertrophy." (PMID 37958246, 2023). "Different from the PSA marker, PCA3 has been detected neither in normal prostate tissues nor in prostatic hyperplasias, and PCA3 can be detected in urine samples from PCa patients with high certainty." (PMID 30761182, 2019). "Unlike PSA, PCA3’s expression remains unaffected in other prostate pathologies, such as chronic prostatitis and benign prostatic hyperplasia (BPH)." (PMID 36551580, 2022). "Unlike PSA, PCA3 expression remains constant during prostatic hyperplasia and prostatitis, thereby making it more sensitive than PSA for PCa detection and it has therefore been suggested that the PCA3 score be used as an exclusion tool." (PMID 27438858, 2016).
prostate (12 papers, 2012 to 2025). "Of note, PCA3 participates in developing prostate malignancy, while RP11-462G22.1 was initially detected as a muscular dystrophy-related lncRNA." (PMID 40584439, 2025). "There are different expression of PCA3 gene in PCa tissue and other noncancerous tissue, which provides a great help for clinician to distinguish PCa from other prostatic diseases." (PMID 31961625, 2020). "PCA3 has been shown to be PCa specific, since its expression is not influenced by other clinical conditions, such as chronic prostatitis, on the contrary of PSA levels." (PMID 31762940, 2019). "We found in the present study that PCA3 is mainly expressed in the nuclear and microsomal subcellular fractions in LNCaP prostate epithelial cells, but not in prostate-tumor stromal cells." (PMID 23130941, 2012). "PCA3 was no different for patients with prostatitis and patients with BPH." (PMID 32630458, 2020). "Besides, PCA3 is also not affected by age, prostate volume or other prostatic diseases." (PMID 31961625, 2020).
breast carcinoma (9 papers, 2013 to 2024). "Contrary to the PCA3 promoter, the PSA chimeric promoter, PSEBC, was highly androgen responsive in AR-expressing PCa cell lines and it was also active in AR-expressing breast cancer cells such as CAMA-1 and ZR-75-1." (PMID 34976196, 2022). "After testing the system in 22Rv1, LAPC4, DU-145 (PCa), CAMA-1 (breast cancer) and SW780 (bladder cancer) cell lines, we observed that orientation A provided the highest reporter gene signal while also being specific to PCa cells due to PCA3-driven Cre expression." (PMID 34976196, 2022). "BMCC1 expression was also absent from the PCA3 negative breast cancer cell line MCF7." (PMID 24040105, 2013).
bladder cancer (3 papers, 2012 to 2022). "Next, we assessed the PCa specificity of our PCA3-3STA construct by comparing its expression level in PCa cell line 22Rv1 to that in the bladder cancer cell line SW780." (PMID 26594800, 2016).
prostatic adenocarcinoma (3 papers, 2011 to 2023). "Relative to controls, PCA3 expression was significantly higher in prostatic adenocarcinoma (mean: 2.46; standard deviation: 1.28) than normal prostate (–1.99; 2.63, [p-value <0.001])." (PMID 36645410, 2023). "We observed a homogeneous nuclei-cytoplasm staining of prostatic adenocarcinoma specimens, probably due to a constant PCA3 RNA production and processing." (PMID 26174796, 2015). "Serial analysis of gene expression has shown that PCA3 expression is significantly and especially up-regulated in the majority of prostatic adenocarcinomas." (PMID 21655300, 2011). "(A) PCA3 and PRUNE2 expression in nonneoplastic prostatic glandular tissue and in prostatic adenocarcinoma in the TCGA cohort illustrating consistent gene expression differences between tumor (n=497) and nonneoplastic (n=52) prostate in both cohorts." (PMID 36645410, 2023).
prostatic hyperplasia (3 papers, 2016 to 2022). "Prostate-specific antigen (PSA), digital rectal examination (DRE), and urinary prostate cancer gene 3 (PCA3) score were used as the diagnostic tools with biopsy as the reference diagnostic tool in the assessment of prostate disorders in the participants." (PMID 36246565, 2022).
atherosclerosis (2 papers, 2019). A disease characterized by the build-up of fatty material and calcium deposition in the arterial wall resulting in partial or complete occlusion of the arterial lumen. "Interestingly, we observed several well-known lncRNAs, such as TUG1, PCA3, and HOTAIR, which were also involved in regulating atherosclerosis progression." (PMID 30873207, 2019).
melanoma (2 papers, 2017 to 2023). A malignant, usually aggressive tumor composed of atypical, neoplastic melanocytes. "These are: MALAT1, NEAT1, PCA3, BCAR4, lncRNA-ATB (CTD−2314B22.3) and the recently-discovered melanoma driver SAMMSON (RP11−460N16.1)." (PMID 28128360, 2017).
ovarian carcinoma (2 papers, 2019 to 2023). A malignant neoplasm originating from the surface ovarian epithelium. "PCA3 knockdown in ovarian cancer cells led to the suppression of cell migration, invasion and viability, besides induction of G1 cell cycle arrest and apoptotic cell death." (PMID 31762940, 2019). "Nevertheless, further data are needed to understand the mechanisms modulating PCA3 expression in ovarian cancer cells." (PMID 31762940, 2019). "The detection of PCA3 in ovarian healthy and cancer tissues, as well as in ovarian cancer cell lines, has been described." (PMID 31762940, 2019). "Furthermore, no expression of PCA3 was found in other normal human tissues, tumors originating from the breast, cervix, or testis, or cell lines originating from the bladder, kidney, or ovarian cancers, confirming PCA3's prostate‐specificity." (PMID 39188554, 2023).
thyroid cancer (2 papers, 2020 to 2022). "The results of this study revealed that the lncRNAs HOTAIRM1 and PCA3 are upregulated during thyroid cancer development and progression." (PMID 32760219, 2020).